ZNF512 (zinc finger protein 512)
Description:
Sequence-specific DNA-binding protein that recognizes repetitive and non-consecutive TTC sequences in pericentric repeat and initiates heterochromatin formation through interaction with SUV39H1/2 methyltransferases which catalyze histone H3K9 methylation.
Synonyms: KIAA1805
Tractability: PROTAC: UniProt records ubiquitination sites on it; ubiquitination databases record sites on it; its protein half-life has been measured.
Gene: Protein-coding gene on chromosome 2 (27,582,969 to 27,623,217, forward strand). Ensembl gene ENSG00000243943.
Subcellular location: Chromosome; Nucleus
Subcellular location (Human Protein Atlas): Nucleoplasm
Gene Ontology:
Molecular function: protein binding; DNA binding; DNA-binding transcription factor activity; zinc ion binding
Biological process: constitutive heterochromatin formation; regulation of DNA-templated transcription; regulation of gene expression
Cellular component: chromosome; nucleus; pericentric heterochromatin
Genetic constraint (gnomAD): Loss-of-function variants: 24 observed, 68.99 expected, observed/expected ratio (o/e) 0.35, 90% interval 0.25 to 0.49. The upper end of that interval is the gene's LOEUF score, 0.49, which puts it in group 2 of 6, group 1 being the genes least tolerant of losing a copy. Missense variants: 435 observed, 642.13 expected, observed/expected ratio (o/e) 0.68, 90% interval 0.62 to 0.73. Synonymous variants: 210 observed, 226.49 expected, observed/expected ratio (o/e) 0.93, 90% interval 0.83 to 1.04.
Homologues: Orthologues: macaque ZNF512 (99% identical), pig ZNF512 (96% identical), dog ZNF512 (90% identical), guinea pig ZNF512 (90% identical), chimpanzee ZNF512 (87% identical), mouse Zfp512 (87% identical), rat Zfp512 (86% identical), rabbit ZNF512 (75% identical), zebrafish znf512 (41% identical), Drosophila melanogaster nahoda (20% identical), Caenorhabditis elegans C09F9.2 (13% identical), Drosophila melanogaster Vajk4 (8% identical), and 2 more. Paralogues in human: ZNF512B (37% identical), GGN (12% identical).
Diseases named in the same sentence as ZNF512 in open-access papers:
ZNF512 is named in the same sentence as 12 diseases in open-access papers, as found by Europe PMC text mining. Sharing a sentence is not in itself a finding about the gene and the disease. The quoted sentences say what the papers report.
breast carcinoma (1 paper, 2021). "Of the remaining 12 genes, seven (A4GALT, C2ORF74, HRCT1, ZC4H2, ZNF512, ZNF655, and ZNF608) show similar relative expression profiles in large patient samples and other breast cancer cell lines thereby giving insight into predicted role of H3K4me3 mediated gene regulation via the miRNA-mRNA axis." (PMID 34261302, 2021).
endometriosis (1 paper, 2025). The growth of functional endometrial tissue in anatomic sites outside the uterine body. "The role of “hubs” in these endometriosis-significant interactions was performed by proteins such as FNDC4 (participates in 9 pair interactions), NRBP1 and ZNF512 (7 pair interactions each), C2orf16, GPN1, and KRTCAP3 (6 pair interactions each)." (PMID 41373783, 2025).
Hypertension (1 paper, 2021). The presence of chronic increased pressure in the systemic arterial system. "Genes C2orf16, ZNF512 and COBLL1 were also previously reported, as was SLC39A8 in chromosome (CHR) 4, which plays a role in hypertension and has been found to be associated to type-2 diabetes." (PMID 34145383, 2021).
liver fibrosis (1 paper, 2022). "Activated TFs ZNF14 and ZNF512 were positively correlated with advanced liver fibrosis." (PMID 36440333, 2022).
oral cancer (1 paper, 2017). "This is notable considering that alcohol consumption is a leading cause of oral cavity cancer, suggesting that the link between ZNF512 and alcohol consumption may underlie its association with oral cancer." (PMID 28937693, 2017).
psoriasis (1 paper, 2025). An autoimmune condition characterized by red, well-delineated plaques with silvery scales that are usually on the extensor surfaces and scalp. "A 2019 proteomic study identified SLFN5 among a set of new disease-associated proteins in psoriasis, alongside other markers (ATM, ZNF512, SPATA13, etc.)." (PMID 41328434, 2025).
cancer (2 papers, 2025). A tumor composed of atypical neoplastic, often pleomorphic cells that invade other tissues. "However, 50 transcription factors displayed similar interactions with SWI/SNF in the two cancer types, such as several zinc-finger transcription factors (ZNF512, ZNF598, ZNF609, ZNF687, and ZNF709), CTCF, ELF2, and YBX1, indicating shared gene regulation networks." (PMID 40988026, 2025).
ZNF512 also shares sentences with these, for which no sentence is quoted: fatty liver (1 paper); neurodegenerative disease (1); oral cavity cancer (1); tumour diseases (1); type-2 diabetes (1).